POLR3K (RNA polymerase III subunit K)
Description:
Core component of RNA polymerase III (Pol III) which synthesizes small non-coding RNAs using the four ribonucleoside triphosphates as substrates. Can mediate Pol I proofreading of the nascent RNA transcript. Anchors into the Pol III active site to constantly monitor transcription fidelity, cleaves mis-incorporated 5'-ribonucleotides and restarts the transcription process. Once Pol III reaches the poly(dT) termination signal, can induce Pol III clamp opening and transcription termination (By similarity). Pol III plays an important role in sensing and limiting infection by intracellular bacteria and DNA viruses. Acts as a nuclear and cytosolic DNA sensor involved in innate immune response. Can sense non-self dsDNA that serves as template for transcription into dsRNA. The non-self RNA polymerase III transcripts, such as Epstein-Barr virus-encoded RNAs (EBERs) induce type I interferon and NF-kappa-B through the RIG-I pathway.
Synonyms: RPC12.5; RPC11; My010; C11; C11-RNP3; HLD21; RPC10
Tractability: Small molecule: a structure with a bound ligand is known. PROTAC: ubiquitination databases record sites on it.
Gene: Protein-coding gene on chromosome 16 (46,407 to 53,658, reverse strand). Ensembl gene ENSG00000161980.
Subcellular location: Nucleus
Subcellular location (Human Protein Atlas): Nucleoplasm; Cytosol
Pathways (Reactome):
Gene expression (Transcription): RNA Polymerase III Abortive And Retractive Initiation; RNA Polymerase III Chain Elongation; RNA Polymerase III Transcription Initiation From Type 1 Promoter; RNA Polymerase III Transcription Initiation From Type 2 Promoter; RNA Polymerase III Transcription Initiation From Type 3 Promoter; RNA Polymerase III Transcription Termination
Immune System: Cytosolic sensors of pathogen-associated DNA
Gene Ontology:
Molecular function: protein binding; zinc ion binding; DNA-directed RNA polymerase activity; nucleic acid binding
Biological process: termination of RNA polymerase III transcription; transcription by RNA polymerase III; transcription initiation at RNA polymerase III promoter; DNA-templated transcription
Cellular component: RNA polymerase III complex; cytosol; nucleoplasm; nucleus
Genetic constraint (gnomAD): Loss-of-function variants: 10 observed, 12.99 expected, observed/expected ratio (o/e) 0.77, 90% interval 0.47 to 1.3. The upper end of that interval is the gene's LOEUF score, 1.3, which puts it in group 5 of 6, group 1 being the genes least tolerant of losing a copy. Missense variants: 144 observed, 150.51 expected, observed/expected ratio (o/e) 0.96, 90% interval 0.83 to 1.1. Synonymous variants: 56 observed, 53.3 expected, observed/expected ratio (o/e) 1.05, 90% interval 0.85 to 1.31.
Gene-disease validity (ClinGen):
ClinGen rates the evidence that POLR3K causes each of these diseases.
leukodystrophy, hypomyelinating, 21 (autosomal recessive): Limited.
Homologues: Orthologues: dog POLR3K (100% identical), chimpanzee POLR3K (99% identical), macaque POLR3K (99% identical), mouse Polr3k (99% identical), pig POLR3K (99% identical), guinea pig POLR3K (98% identical), rabbit POLR3K (97% identical), zebrafish polr3k (93% identical), tropical clawed frog polr3k (90% identical), Drosophila melanogaster Polr3K (70% identical), rat Polr3k (69% identical), Caenorhabditis elegans rpc-11 (61% identical). Paralogues in human: POLR1H (28% identical), POLR2I (23% identical).
Diseases named in the same sentence as POLR3K in open-access papers:
POLR3K is named in the same sentence as 10 diseases in open-access papers, as found by Europe PMC text mining. Sharing a sentence is not in itself a finding about the gene and the disease. The quoted sentences say what the papers report.
leukodystrophy (11 papers, 2019 to 2024). Leukodystrophies are a group of rare, progressive, metabolic, genetic diseases that affect the brain, spinal cord and often the peripheral nerves. "In addition, an ever-increasing number of distinct mutations in the POLR3A, POLR3B, POLR1C and POLR3K subunits cause a spectrum of neurodegenerative diseases, which includes most notably hypomyelinating leukodystrophy." (PMID 34395528, 2021). "In another study, mutations in POLR3K were recently identified in two patients with leukodystrophy." (PMID 30898877, 2019). "POLR3-related leukodystrophy is caused by biallelic pathogenic variants in genes encoding subunits of Pol III, i.e. POLR3A, POLR3B, POLR1C and POLR3K." (PMID 36451185, 2022). "4H leukodystrophy has been found to be caused by biallelic pathogenic variants in POLR3A, POLR3B, POLR1C, and POLR3K, each of which encode subunits of the POLR3 complex." (PMID 33005949, 2021). "Mutations in genes encoding subunits of the transcription complex RNA polymerase III (POLR3), namely POLR3A, POLR3B, POLR1C, POLR3K and POLR3GL might cause a particular type of hypomyelinating leukodystrophies known as Pol III-related leukodystrophies." (PMID 33804237, 2021). "4H or POLR3-related leukodystrophy is an autosomal recessive disorder typically characterized by hypomyelination, hypodontia, and hypogonadotropic hypogonadism, caused by biallelic pathogenic variants in POLR3A, POLR3B, POLR1C, and POLR3K." (PMID 33005949, 2021). "POLR3-HLD, also termed 4H (Hypomyelination, Hypodontia, and Hypogonadotropic Hypogonadism) leukodystrophy, is caused by biallelic pathogenic variants in genes encoding subunits of the ubiquitous RNA polymerase III (Pol III) enzymatic complex (e.g., POLR3A, POLR3B, POLR1C, POLR3K, and POLR3D)." (PMID 39062571, 2024).
glioma (1 paper, 2024). A benign or malignant brain and spinal cord tumor that arises from glial cells (astrocytes, oligodendrocytes, ependymal cells). "The results indicated that AMT, AS3MT, EGFR, NICN1, and POLR3K exhibited significant sex differences in expression within glioma tissues." (PMID 39722126, 2024).
cancer (1 paper, 2023). A tumor composed of atypical neoplastic, often pleomorphic cells that invade other tissues. "POLR3K may contribute to the proliferation and angiogenesis of cancer cells by inducing NF-B signaling." (PMID 37333985, 2023).
POLR3K also shares sentences with these, for which no sentence is quoted: hypogonadotropic hypogonadism (3 papers); apraxia (1); attention deficit-hyperactivity disorder (1); Hypodontia (1); Intellectual disability (1); neurodegenerative disease (1); Speech apraxia (1).